MUC1 (mucin 1, cell surface associated)
Diseases named in the same sentence as MUC1 in open-access papers (continued):
Sharing a sentence is not in itself a finding about the gene and the disease.
infection (continued). "A time-course over the first 72 h of infection showed significantly higher mucosal loads of bacteria at 8 h of infection in Muc1−/− mice compared with WT, confirming its importance in the early stages of infection (P = 0.0003)." (PMID 32793510, 2020). "As infection progressed, a network of antimicrobial and anti-inflammatory response genes was more highly activated in Muc1−/− than WT mice." (PMID 32793510, 2020). "This cluster contained Acta1, encoding smooth muscle actin, as well as the actin crosslinking protein gene Actn3 and two myosin genes (Myo1h and Myh2), suggesting that both infection and Muc1 knockout disrupt the cytoskeleton." (PMID 32793510, 2020). "For instance, we observed that the genes encoding interferon induced protein 44 (Ifi44 gene) and schlafen family member 12 like (Slfn12l gene) are two of the most highly induced genes in Muc1−/− mice vs. WT at 24 h post-infection." (PMID 32793510, 2020). "BALB/c mice were infected with HMPV, and the expression of Muc1, Muc2, Muc4, Muc5ac, Muc5b, Muc15, Muc16, Muc19, and Muc20 were analyzed at 12, 24 and 48 h after infection." (PMID 32899224, 2020). "Compared to uninfected cells, HMPV infection induced a significant fold-increase expression of MUC1 (8.3 ± 2), MUC2 (43.4 ± 13), MUC4 (54 ± 12), MUC5ac (23.3 ± 11.5) and MUC19 (77 ± 35), while no significant induction of MUC15, MUC16 and MUC20 was observed." (PMID 32899224, 2020). "Overall, the existing data indicate that MUC1 plays an important anti-inflammatory role during infection with different bacterial pathogens at the respiratory mucosa." (PMID 33184103, 2020). "A higher number of infected cells is consistent with the higher H. pylori colonization in the gastric mucosa of Muc1−/− mice throughout the first 3 days of infection." (PMID 32793510, 2020). "It is now clear that MUC1 plays an integral role in regulating inflammatory responses to infection and is a key modulator in controlling pathogen-induced inflammatory disease." (PMID 31069176, 2019). "Salmonella apical infection efficiency clearly coincided with the level of MUC1 expression by these cell types." (PMID 30716138, 2019). "Clearly, MUC1 plays a dynamic role in the mucosal barrier to infection and regulation of innate immune responses to control inflammation." (PMID 31069176, 2019). "In the murine P. aeruiginosa infection model, reduced colonization of P. aeruginosa in Muc1−/− mice was due to enhanced clearance via heightened early inflammatory responses to the infection, compared to that observed in WT mice." (PMID 31069176, 2019). "At 8-days post-infection in Muc-1 wildtype mice, when most acinar cells were lost, Muc-1 expression was detected in remaining ductal structures." (PMID 31337812, 2019). "Opposite to the effects of the MUC1 barrier to infection in the intestinal tract, studies reveal a reduced colonization of P. aeruginosa in lungs of Muc1−/− mice as compared to wild-type (WT) mice." (PMID 31069176, 2019). "We report that knockout of Muc-1 reduced the degree of pancreatic inflammation that resulted from infection with Coxsackievirus B3 (CVB3) in a mouse model." (PMID 31337812, 2019). "Linking both barrier and immunomodulatory function of MUC1 during IAV infection, Muc1−/− mice reached maximal viral titers earlier than the WT mice, but also exhibited enhanced inflammatory responses to the infection when viral titers were equivalent." (PMID 31069176, 2019). "The degree to which MUC1 inhibition of activated TLR pathways diminishes inflammatory responses to infection and the critical timing to which this occurs in vivo remains to be elucidated, however must play a significant role in controlling disease severity." (PMID 31069176, 2019). "Using an in vivo model of infection, MUC1 expression at the epithelial surface was shown to limit gastrointestinal and systemic spread of C. jejuni and reduce intestinal inflammation in mice." (PMID 31069176, 2019).
infection (continued). "There is evidence that MUC1 is a physical barrier to protect gastric mucosa from Hp dwelling in murine infection model and in vitro experiment; in turn, by injuring the physical barrier, Hp infection would decrease the expression of MUC1." (PMID 29849739, 2018). "MF (indicative of reproductive fitness and parasitic success) was reduced by approximately 40% in plants infected with Mi‐muc‐1 dsRNA‐treated J2s, as compared with infection with freshly hatched and dsGFP‐treated J2s." (PMID 30011135, 2018). "For MUC1 rs4072037, similar significant associations between PRKAA1 rs13361707 and decreased risk of GC were found in subjects with both Types I and II infection." (PMID 28220687, 2017). "In Muc1+/+ mouse lungs, Muc1 levels were low both in uninfected and infected lungs at early time points following infection." (PMID 29186029, 2017). "It is thought that MUC1 exerts anti-inflammatory effects upon infection with pathogens by suppressing pro-inflammatory cytokines such as Tumor Necrosis Factor-alpha (TNF-α)." (PMID 29268739, 2017). "Muc1 levels increased post-infection, reaching maximum levels after two days which were maintained even seven days post-infection." (PMID 29186029, 2017). "Mostly studied for its role in various forms of cancer, MUC1 is widely regarded as playing an anti-inflammatory role in response to infection with bacterial pathogens in various tissues." (PMID 28588132, 2017). "For example in respiratory epithelia, MUC1 negatively regulates TLR signaling in response to infection and inflammation." (PMID 24968021, 2014). "The mRNA levels of the Muc1, 2, 4 and 13 mucins were all increased (4–9 fold) during the earliest time points of infection." (PMID 24386378, 2013). "H. pylori binds directly to purified MUC5AC and MUC1 mucins and MUC1 has been shown to be important in limiting infection by Helicobacter and Campylobacter in a mouse model of infection." (PMID 23056622, 2012). "The shedding of the extra cellular portion of MUC1 has been studied in infection and is considered to be a reaction of the molecule to changes in its environment that then signals the cell to which it is attached." (PMID 20806091, 2010). "The cell-surface mucin MUC1 is highly expressed on the mucosal surface and limits the density of H. pylori in a murine infection model." (PMID 19816567, 2009). "The cell-surface mucin MUC1 is a large glycoprotein which is highly expressed on the mucosal surface and limits the density of H. pylori in a murine infection model." (PMID 19816567, 2009). "In vitro infection of the MUC-1-positive breast cell line T47D resulted in virus replication, cytolysis, and release of infective viral particles." (PMID 19635153, 2009). "In the distal colonic epithelium, all secreted and cell surface mucins decreased with the exception of the Muc1 cell surface mucin which increased after infection (p<0.05)." (PMID 19088856, 2008). "In the murine infection model of C. jejuni, Muc1 is upregulated acutely in the intestine in response to infection." (PMID 19088856, 2008). "We now show that C. rodentium infection also induces Muc1 in mouse colon, and similarly that S. St Paul, C. jejuni and C. difficile induced MUC1 in human colon during infection." (PMID 19088856, 2008). "The cellular content of most mucins changes in response to infection, with Muc1 being the only mucin to be induced whereas all other mucins were depleted, albeit to differing degrees." (PMID 19088856, 2008). "Thus, the effects of TILT-322 infection can be seen in the lower expression of MUC1 antigen-expressing ascites cells and higher lymphocytes." (PMID 38910324, 2024). "Given the protective role of MUC1 during infection, the high levels of the inflammatory cytokines may have induced higher MUC1 expression from epithelial cells to limit RSV-induced progressive inflammation." (PMID 38036963, 2023). "MUC1 plays an anti-inflammatory role in many infections and chronic inflammatory lung diseases." (PMID 38036963, 2023).
infection (continued). "The pattern of expression of airway surface liquid (ASL) homeostasis-associated genes (CFTR, BPIFA1, MUC1, MUC5AC, MUC5B) in the PCLS varied greatly between the three strains, and only infection with strain T15 induced statistically significant changes in this group of genes." (PMID 38276150, 2023). "Additionally, our results demonstrate that MUC1 significantly reduces IAV replication by acting early in infection, consistent with its canonical role as a barrier protecting the airway epithelium." (PMID 35699372, 2022). "MUC1 has the potential to influence infection dynamics through physical interactions and/or signaling activity, yet MUC1 modulation and its impact during viral pathogenesis remain unclear." (PMID 35699372, 2022). "As we investigated only the earliest steps in IAV infection of HAE, future studies should interrogate how viral-mediated upregulation of MUC1 may impact subsequent spread and immune response to an established infection." (PMID 35699372, 2022). "Similarly, infection of HAE with A/Udorn/307/72 (500 PFU; approximate MOI of 0.01) was associated with ubiquitous MUC1 protein expression throughout the epithelium by 48 hpi (right)." (PMID 35699372, 2022). "To assess whether IAV was better able to initiate successful infection of MUC1 KO cultures, we tabulated the number of viral antigen-positive foci on predetermined regions of infected cultures 12 hpi." (PMID 35699372, 2022). "Prophylactic treatment of GG was found to significantly inhibit the expression of surfactant protein D (sftp-D) and plasminogen activator inhibitor-1 (PAI-1) while reducing the expression of mucin-1 (muc1) and exotoxin to 1.5- to 2-fold as compared to the infection control." (PMID 36238303, 2022). "Indeed, the surprising finding that MUC1 is upregulated beyond the apical layer supports a broader dynamic role during infection at the epithelial surface." (PMID 35699372, 2022). "Similarly, Muc1−/− mice showed a five times higher density of infection (increased colony forming units) as early as 1 day after oral gavage with H. pylori compared with WT mice." (PMID 35774401, 2022). "Infection of the DOX+ MUC1-YF cells with E. coli inv showed a 30% reduction in the number of infected cells for the subset of MUC1-YF expressing cells compared to DOX− MUC1-YF cells, suggesting that tyrosine residues in the MUC1 CT play a role in ITGB1-mediated bacterial uptake." (PMID 33824202, 2021). "Both models predict the influence of MUC1 on various infection-related quantities." (PMID 34066999, 2021). "Combined with the observation that MUC1-KO mice clear virus after day 7 post infection, the effects of MUC1 may be minimally influenced by the detailed dynamics of adaptive immunity." (PMID 34066999, 2021). "NEU1 desialylates the MUC1-ED to unmask a cryptic Gly-Ser protease recognition site, thereby permitting the shedding of soluble MUC1-ED that functions as a decoy receptor to competitively inhibit Pa from establishing an invasive infection." (PMID 34688655, 2021). "The number of DE genes was higher in Muc1−/− mice than WT mice at 8 h post infection; the higher number of DE genes could be a consequence of the higher colonization levels of H. pylori in Muc1−/− mice." (PMID 32793510, 2020). "In addition, higher expression of solute carrier family genes (Slc13a1, Slc26a3, Slc2a2, Slc40a1, Slc5a1, and Slc6a19) was seen in the gastric tissue of Muc1−/− mice compared with WT at sham and 8 h infection." (PMID 32793510, 2020). "However, H. pylori infection resulted in ~2–6-fold induction of most of these genes in WT at 24 h, vs. a ~2-fold decreased expression in Muc1−/− gastric tissues, and a similar trend was seen at 72 h infection." (PMID 32793510, 2020). "The higher bacterial burden could cause more tissue damage in the gastric mucosa of Muc1−/− mice compared with WT mice, thus the activation of this pathway is likely to stimulate repair at sites of infection and epithelial injury in Muc1−/− mice." (PMID 32793510, 2020).
infection (continued). "In addition, sham and 8 h infected Muc1−/− samples were more similar to the WT 24 and 72 h infection samples than the earlier time points in WT." (PMID 32793510, 2020). "In addition to bacterial pathogens, MUC1 (over)expression also reduced infection by adenoviruses and influenza A." (PMID 30716138, 2019). "However, there is burgeoning evidence that MUC1 plays a dynamic role in the host mucosal barrier to infection." (PMID 31069176, 2019). "Importantly, MUC1 has been shown to not only provide a physical barrier, limiting infection and colonization, it has also been demonstrated to play a significant role as a modulator of pathogen-induced inflammation." (PMID 31069176, 2019). "With respect to its physiological function in the mucosal environment, MUC1 has been demonstrated to play a dynamic role in protection of the host from infection by a wide variety of pathogens and to regulate inflammatory responses to infection." (PMID 31069176, 2019). "Infection with an HB101 strain expressing AAF/II-encoding genes also increased MUC1 expression, thus strongly suggesting that AAFs are sufficient to trigger elevated MUC1 expression on the intestinal epithelium." (PMID 28588132, 2017). "However, infection of mice with either Campylobacter jejuni or Citrobacter rodentium leads to increased MUC1 expression in inflamed intestines." (PMID 28588132, 2017). "Moreover, we find that MUC1 facilitates AAF-dependent migration of neutrophils across the epithelium in response to EAEC infection." (PMID 28588132, 2017). "Our results identifying a proinflammatory role for MUC1 in response to an intestinal pathogen are novel and suggest that the role of MUC1 in inflammation is complex and likely depends on a variety of factors, including the specific pathogen and the site of infection." (PMID 28588132, 2017). "In addition, Muc1−/− mice also had increased post-infection levels of proinflammatory keratinocyte chemoattractant (KC) and TNF in their bronchoalveolar fluid (BALF), and greater levels of BALF leukocytes compared with Muc1+/+ mice." (PMID 29186029, 2017). "Studies were then undertaken to determine whether simultaneous infection of human DCs with the CEA/MUC1/brachyury mixture of Tri-Ad5 could generate T-cell lines specific for all three TAAs." (PMID 26374823, 2015). "Similarly, epithelial-derived MUC1 in breast milk, which contains multiple repeating LewisX motifs, has been implicated in preventing cell-free HIV-1 transmission to DC and infection of CD4+ T cells." (PMID 22952771, 2012). "Thus, Muc1/MUC1 is induced in response to infection by a range of different pathogens in both mice and humans." (PMID 19088856, 2008). "Similarly, during human infection Salmonella St Paul, Campylobacter jejuni and Clostridium difficile induced MUC1 in the colon." (PMID 19088856, 2008). "Thus, MUC1 is induced in response to infection by a range of different intestinal pathogens in humans, in a similar manner to the induction we demonstrated experimentally in C. rodentium infection in mice." (PMID 19088856, 2008). "Notably, infection of HAE with H1N1 or H3N2 IAV strains does not trigger MUC1 shedding but instead stimulates an increase in cell-associated MUC1 protein." (PMID 35699372, 2022). "MUC1 expression limited the severity of influenza A virus infection in both human and mouse airway epithelial cells, although the mechanism was hypothesized not to be mediated through the MUC1-CT, but rather to involve virus binding to the MUC1 ectodomain, blocking subsequent host cell infection." (PMID 29186029, 2017). "Interestingly, MUC1 is known to display a regulatory role in mucosal immunity and is primarily involved in the formation of a physical barrier to lubricate and protect normal epithelial tissues, limiting infection and colonization, and mediating signal transduction." (PMID 41295249, 2025).
infection (continued). "The results showed that 0.5 ml of the viral supernatant infection yielded 15% of the DCs expressing TNF, with similar infection efficacy with chimeric CD66b-Muc1 scFv." (PMID 39105847, 2024). "Following infection with SARS-CoV-2, multiple mucin genes showed significantly positive correlations in the digestive tissues, particularly MUC1, MUC12 and MUC13." (PMID 38563680, 2024). "In contrast, G5P infection decreased expression of transmembrane mucin genes significantly (MUC12, MUC16 and MUC21) or numerically (MUC1, MUC4, MUC13 and MUC20)." (PMID 37848925, 2023). "Lastly, alternative splicing of MUC1 and PMF1 had high posterior probabilities for reported infection (1.00 and 0.95, respectively)." (PMID 37794074, 2023). "The IAV hemagglutinin protein binds MUC1 isolated from HAE apical secretions and colocalizes with MUC1 during infection." (PMID 35699372, 2022). "Infection then stimulates MUC1 expression on multiple cell types through IFN-dependent and -independent mechanisms that further impact infection dynamics." (PMID 35699372, 2022). "To determine the impact of membrane-anchored mucins on infection of diverse SARS-CoV-2 clinical isolates, we infected our MUC1 and MUC4 GOF Calu-3 lines with alpha (B.1.1.7), beta (B.1.351), gamma (P.1), epsilon (B.1.429) and WA/1 variants." (PMID 35879412, 2022). "Models of Pseudomonas aeruginosa bacterial infections revealed that mucin 1 (MUC1) mediated bacterial adherence, dampened inflammation, and facilitated infection in airway epithelium." (PMID 36675861, 2022). "Our results support a direct interaction between IAV and endogenous MUC1 during infection in HAE, extending previous findings that demonstrated colocalization of IAV with MUC1 on the surface of A549 cells." (PMID 35699372, 2022). "Combined with its catalytic role in generating a hyperadhesive, shed MUC1-ED decoy receptor, NEU1 offers a bipartite level of regulation over the airway epithelial response to Pa colonization and/or infection." (PMID 34688655, 2021). "MUC1 and MUC4 are closely related mucins; MUC4 had the strongest inhibition among these SHREKs in our infection assay." (PMID 34064525, 2021). "In high MUC1 expressing CAPAN-2 cells, infection with PCVV was reduced compared to VV, while infection was restored with aMUC1-PCVV." (PMID 33869742, 2021). "In our study, C. rodentium-challenged mPG-1- and C. rodentium-challenged ProPG-1-treated mice showed increased Muc1 gene expression relative to C. rodentium-challenged PBS-treated mice, suggesting enhanced protection from the infection." (PMID 34502403, 2021). "MUC1 also inhibits signaling of other TLRs, including TLR2, TLR4, TLR7, and TLR9, during infection with respiratory syncytial virus." (PMID 33184103, 2020). "It is also known that host cells respond to invading Campylobacter by upregulating MUC1 production, which partially protects them from the actions of CDT, thus defending not only against the infection but also against potential DNA damage." (PMID 33050171, 2020). "We confirmed Muc-1 expression during pancreatic injury by immunofluorescence on tissue collected from CVB3 infected WT and Muc-1KO mice pancreata 8-days post-infection." (PMID 31337812, 2019). "Furthermore, mice lacking the Muc1 mucin are more susceptible to infection by H. pylori." (PMID 30298790, 2018). "We found that infection with EAEC 042 strongly upregulated epithelial MUC1 expression and that stimulation of MUC1 expression depended on bacterial expression of AAFs." (PMID 28588132, 2017). "Reduction of MUC1 expression profoundly reduced the ability of EAEC strains 042 and C227-11 φcu to induce PMN migration compared with infection of control cells." (PMID 28588132, 2017). "In the gastric mucosa, Muc1−/− mice had increased macrophage inflammatory protein-2α (MIP-2α) levels and greater neutrophil-driven inflammation following experimental infection by H. pylori." (PMID 29186029, 2017).